CD34 (CD34 molecule)
Diseases named in the same sentence as CD34 in open-access papers (continued):
Sharing a sentence is not in itself a finding about the gene and the disease.
tumor (continued). "In fact, CD34, a glycophosphoprotein, normally expressed by mature endothelial cells, mesenchymal and hematopoetic progenitor cells, and more importantly in neural stem cells is also localised in MPNSTs tumours, probably in endoneurial fibroblasts." (PMID 21695156, 2011). "Immunostain for CD34 was diffusely positive in this area of tumor." (PMID 21338527, 2011). "Thus any role for CD34 in tumor progression is likely restricted to a tumor cell-extrinsic function in the tumor microenvironment." (PMID 21494591, 2011). "The tumor cells showed positive immunohistochemical reactions to CD34 and bcl-2." (PMID 22192457, 2011). "Immunohistochemistry reveals the tumor cells to be positive for α smooth muscle actin CD34." (PMID 21714873, 2011). "At the same time, an increased CD34 stain was present in the tumor." (PMID 21338527, 2011). "At an early time-point (day 14), loss of CD34 on non-hematopoietic cells affected tumor vasculature resulting in decreased tumor size, increased vascular leakage and altered vessel morphology." (PMID 21494591, 2011). "As CD34 is expressed on the vascular endothelia, we characterized the expression pattern of CD34 in wildtype tumor tissue, and also confirmed its absence on Cd34−/− tumor vessels by staining tissue sections with antibodies recognizing CD34." (PMID 21494591, 2011). "Intriguingly, we found that CD34 plays a biphasic role in tumor progression." (PMID 21494591, 2011). "Immunohistochemically, the tumor cells are diffusely positive for vimentin and CD34." (PMID 22567356, 2011). "Thus we propose that the impaired intra-tumoral mast cell and eosinophil infiltration, in Cd34−/− mice, results in decreased tumor clearance and increased tumor growth at the late time-point." (PMID 21494591, 2011). "Their findings may explain the disappearance of CD34 expression in PADI4-expressing tumour cells observed in our study." (PMID 20222985, 2010). "The microvessel density (MVD) within the tumor was determined by immunohistochemistry for CD34." (PMID 20170548, 2010). "Immunohistochemically the tumour cells showed an expression of Vimentin and CD117, a focal expression of CD34, smooth-muscle-actin (not shown) and a nuclear expression of the proliferation-associated Ki-67-antigen in approximately 5-10% of the tumour cells." (PMID 20515511, 2010). "In DF, tumor cells are positive for factor XIIIa and are rarely positive for CD34." (PMID 20525288, 2010). "In addition, tumor vascularization was evaluated by CD34 antigen staining in sections of tumors recovered from control and HB-19 treated RET mice." (PMID 20573279, 2010). "Additionally, immunostaining using CD34 as a marker is helpful in identifying tumor cells at the surgical margins, particularly when treating recurrent DFSP, in which tumor cell fascicles are often interspersed with the scar tissue." (PMID 20525288, 2010). "Therefore, we assessed microvessel density (MVD) in the tumor sections stained with the anti-CD34 antibody." (PMID 20170548, 2010). "Because there are more CD34+ cells expressing PADI4 in tumour tissues than in normal tissues, it is postulated that the development of PADI4-expressing tumour cells may be associated with the abnormal proliferation of CD34+ stem cells or their progeny." (PMID 20222985, 2010). "To examine whether WP1066 inhibits tumour angiogenesis, we immunostained xenograft tumours with CD34 and measured the length of CD34-positive vessels in each tumour (lower row)." (PMID 20461084, 2010). "Similarly, in the present case, CD34-positive cells were found around the Meissner bodies in the tumor sheets." (PMID 20858283, 2010). "Such a down-regulation of CD34 adhesion molecules may allow tumour cells to escape immune surveillance." (PMID 20222985, 2010). "Immunohistochemistry was performed for anti-CD34 antibody to visualize tumor vascularisation." (PMID 19902004, 2009).
tumor (continued). "Another effect that may contribute to decreased tumor size and tumor cell survival in alendronate-treated mice is inhibition of angiogenesis, as suggested by a decreased density of CD34-positive blood vessel capillaries." (PMID 18371232, 2008). "On univariate survival analysis, age (P<0.10), tumour size (P<0.10), lymph node involvement (P<0.05), albumin (P<0.01), microvessel density CD34+ (P<0.10), locoregional treatment (P<0.01) and systemic treatment (P<0.10) were significantly associated with overall survival." (PMID 18797461, 2008). "The failure to demonstrate CD34 in tumor vascular endothelial cells was not caused by the quality of anti-CD34 antibody because the same antibody strongly stained the normal endothelial cells in the placental sections mounted on the same slides." (PMID 18286204, 2008). "In all patients, high tumour grade was positively associated with negative hormonal receptor status (P<0.001), high Ki-67 labelling index (P<0.001) and high expression of CD34+ (P<0.01), CD68+ (P<0.05), CD4+ (P<0.05) and CD8+ (P<0.05) T lymphocytes." (PMID 18797461, 2008). "Only CD34 showed consistent positive staining in tumor tissue." (PMID 19662192, 2007). "Tumor angiogenesis was evaluated on paraffin-embedded sections using CD34 immunostaining." (PMID 17908302, 2007). "Immunohistochemically, the tumor cells showed strong positivity for CD34." (PMID 16859564, 2006). "In the present case strong positivity for CD34 immunostaining was observed in tumor cells." (PMID 16859564, 2006). "To strengthen the hypothesis that PRL-3 plays a role in tumour angiogenesis we performed confocal immunofluorescence of PRL-3 and CD34, a specific marker for endothelial cells, widely used in microscopic evaluation of tumour angiogenesis." (PMID 16832410, 2006). "We could demonstrate that PRL-3 is expressed in CD34-positive endothelial cells and microvessels as well as in CD34-negative tumour cells." (PMID 16832410, 2006). "Widespread staining for CD34 was seen in all tumor specimens." (PMID 15743540, 2005). "In addition, we studied the tumour proliferation rate using the Ki-67 index and tumour angiogenesis using CD34 staining." (PMID 15785747, 2005). "Both the apparent loss of LYVE-1 expression and the gain of CD34 expression indicate paracrine interactions between tumour cells and co-opted endothelial cells, yet without eliciting angiogenesis or desmoplasia." (PMID 15054467, 2004). "The reduction of the number of contaminating tumour cells by CD34+ cell selection might also play a role in survival by preventing the infusion of higher numbers of tumour cells that might overwhelm the immune system and result in relapse." (PMID 12799629, 2003). "While anti-CD105 antibody specifically reacts with endothelial cells of blood vessels in tissues undergoing angiogenesis, anti-CD34 antibody generally binds to endothelial cells in large blood vessels, although its expression can be diminished or restricted in some tumour microvessels." (PMID 12085206, 2002). "Anti-CD34 antibody was used to measure angiogenesis in tumour samples." (PMID 12085206, 2002). "Finally, NAC-HCPS markedly reduced the number of CD34-positive vessels (a marker of microvascular endothelial cells) in subcutaneous 3LL tumours." (PMID 12087470, 2002). "The density of CD34+ vWF- or CD141+/vWF- vessels could thus reflect the rate tumour angiogenesis and the consequences it has for the biological behaviour of DCIS." (PMID 11953822, 2002). "However, there are a number of articles reporting that BCCs’ tumor stroma, to a lesser degree, also may express extravascular presence of CD34, questioning the role of CD34 as a reliable marker for differential diagnosis between these two conditions." (PMID 41597444, 2026). "In addition, BYJHD markedly suppressed the expression of CD34 in tumor tissues." (PMID 41579221, 2026). "The mechanism underlying the absence of CD34 positivity in stromal cells of invasive tumor stroma remains unknown." (PMID 41597444, 2026).
tumor (continued). "Moreover, cancer.cell.2, cancer-associated C3+ fibroblasts (CAF_C3), and Fibrocyte_CD34, which are prone to accumulate in the metastatic site and post-NACT group, harbored poor clinical outcome, reflected in the immune exclusion and tumor progression signaling." (PMID 40725006, 2025). "Although the tumour and its surrounding tissues were resected entirely in this case (pseudo envelope intact), postoperative pathology revealed microvascular penetration (CD34 microvascular endothelium +, densely packed) in the fibrous septa, suggesting the presence of subclinical satellite foci." (PMID 40313252, 2025). "Notably, tumor cells typically lack expression of CK, CD34, CD31, and S100 protein." (PMID 40554936, 2025). "Similarly, the CD34+CLDN5+ cells were existed in tumor samples of patient." (PMID 39674501, 2025). "PTTs may express CD34 and calretinin, which can help distinguish them from other neoplasms." (PMID 40308391, 2025). "Overall, this exploratory analysis with machine learning algorithms suggested that blood CD34+/CD45dim/CD117+ cells might be associated with tumor resistance to both antiangiogenic and non-antiangiogenic therapies." (PMID 39941866, 2025). "Furthermore, as potential differences in the sample composition might interfere with the expression pattern, subsequent studies should include analyses of CD34+ cells or FISH to extrapolate the tumor cell count." (PMID 41488007, 2025). "In the Dabska tumor (papillary intralymphatic angioendothelioma), meshes, covered by aggregates of voluminous CD34 and D2-40 positive endothelial cells, with high nuclear cytoplasmic ratio and moderate mitotic activity, appeared as tufts and could adopt a glomeruloid aspect." (PMID 38397861, 2024). "The expression of CD34 may be related to the abnormal neovascularization in the tumor." (PMID 39220650, 2024). "We previously reported that melanoma brain metastasis tumor volume is positively associated with cerebral edema, but neither variable correlates with intracranial CD34 blood vessel density, which we confirm in the current study using an alternative quantification technique." (PMID 38635031, 2024). "Therefore, the abnormal investment of some tumor-associated capillaries with contractile pericytes (immature; AQP1+CD34+αSMA+) may indicate a dysfunctional phenotype." (PMID 38361951, 2024). "We hypothesize that the GNT CD34+ cells transcriptionally resemble embryonic neuroectodermal (neural precursor) cells that may serve as progenitors for the other neuron-like and macroglia-like tumor cells." (PMID 36966348, 2023). "Therefore, the abundance of CD34 - labelled microvessels represents the most malignant tumor area, which may be reflected using the heterogeneity index α." (PMID 37182187, 2023). "In addition to CD31, endothelial cells resulting from tumour cell transdifferentiation were reported to express various other markers that are generally considered to be vascular endothelial cell-specific, such as CD34, vWF, and VE-cadherin." (PMID 36823554, 2023). "Therefore, CD34+ staining may well represent rapidly budding tumor vessels within CRLM and was used for later analysis." (PMID 36781833, 2023). "However, the number of PAS(+)/CD34(+) vessels was comparable among the three tumor groups." (PMID 35737114, 2022). "Additionally, we analyzed CD34-stained specimens to assess MVD at the tumor invasive front." (PMID 35208526, 2022). "In addition, the PAS+CD34− GC tumor cells expressed high levels of CXCL8 in EBVaGC." (PMID 35321317, 2022). "Here, expressions of VEGF and CD34 in the transplanted tumor tissues after bevacizumab treatment were lower, but HIF-1α expression was significantly higher than those in the control group, suggesting that the anti-angiogenic property of bevacizumab may exacerbate the hypoxic condition in the TME." (PMID 36046821, 2022).
tumor (continued). "Therefore, we developed and characterized humanized patient-derived xenograft (hu PDX) murine models of HGSOC, which were established by orthotopic implantation of tumor cell suspensions and intravenous injection of CD34+ cells isolated from umbilical cord blood samples." (PMID 35804867, 2022). "Moreover, tumors with the morphological feature “vessels encapsulating tumor clusters” as identified by anti-CD34 immunohistochemistry, which has been previously demonstrated to be associated with vascular invasion and short patient survival, exhibited significantly higher Tak1 levels." (PMID 35053591, 2022). "In addition, the expression of CD34 in new vessels—tiny ones, compared to large ones, considered to be old vessels—in the tumor microscopic field suggests and strengthens the idea that this vascular marker plays a crucial role in the process of tumor neoangiogenesis." (PMID 35884977, 2022). "Furthermore, FLAP is closely associated with neovascularization (including tumor angiogenesis) and cell proliferation in resection tissues of HCC patients, evidenced by high expression of FLAP or Ki-67, and neovascular localization of CD34 in parallel." (PMID 35978827, 2022). "However, the in situ assessment of the density of blood vessels stained by specific markers such as CD31 or CD34 was shown to correlate with the aggressiveness of the tumor in a variety of tumor types such as CRC, breast cancer, gastric cancer, and small cell and non-small cell lung cancer." (PMID 33917241, 2021). "Furthermore, VM structures were formed by tumor cells, so VM could be examined by double staining of the endothelial cell marker CD34 and PAS." (PMID 33320958, 2021). "Additionally, tumors with vessels encapsulating tumor clusters (VETC) pattern (as determined by CD34 immunohistochemistry), a morphological feature previously shown to be associated with vascular invasion and worse prognosis, exhibited significantly higher CAD levels." (PMID 33670206, 2021). "Transplanted CD34+ HSCs in immunocompromised mice differentiate into human helper T cells, cytotoxic T cells, B cells, monocytes, NK cells, and dendritic cells; after tumor implantation, these mice can survive several months with a relatively stable percent of human cells in the blood." (PMID 33572835, 2021). "In addition, MVD of intratumoral CD34(+) vessels correlated with tumor volume in tumors with a DLM." (PMID 34942951, 2021). "Our study suggested that the tumor tissue from intravenous microbubbles combined with ultrasonic exposure treatment decreased expression of CD34 compared with other groups, and the treatment of intravenous microbubbles combined with ultrasonic exposure may inhibit angiogenesis." (PMID 33547949, 2021). "However, CD34 MVD in Notch 1 hot spots may be a new prognostic factor with different means from CD34 MVD measured in the entire tumor tissue." (PMID 34642389, 2021). "Moreover, it has been indicated that the inhibition of CD34 expression may repress neoangiogenesis, tumor growth and invasion." (PMID 34660264, 2021). "DCs with a weak expression of CD34 also correlated with the presence of capillaries in the solid tumor component (gamma = 0.528; p = 0.001) and the number of the lymphatic vessels in the lymphoid and polymorphic cell infiltrates of tumor stroma (gamma = 0.706; p = 0.0002)." (PMID 32849870, 2020). "Indeed, this original observation raises the question of whether TCs/CD34+SCs act as nurse and/or insulating cells in specific types of tumours." (PMID 33353193, 2020). "It was elucidated in our study that the NK cells can be differentiated from CD34+ cells isolated from cord blood and is capable to induce apoptosis with increased antitumor potential in vitro against different cancer cells via downregulation of survivin gene expression in tumor cells." (PMID 32592353, 2020).
tumor (continued). "This subset of ILC with loss of CD34+ fibroblasts resembles the stromal characteristics of IBC-NST, whereas 26% of the studied cases demonstrate a predominantly or uniformly positive tumor stroma for CD34+ fibroblasts, pointing to the existence of distinct stromal subtypes for ILC." (PMID 32435886, 2020). "CD34 positive TCs may act as progenitor cells, a nurse of stem cells, and a source of fibroblasts and myofibroblasts during tissue repair in fibrosis, granulation tissue, and tumor stroma." (PMID 33377639, 2020). "Thus, to determine whether a differential degree of vasculature was present between parental and holoclone-derived tumours, a subset of tumour sections (n = 3) were chosen for IHC staining with the vascular marker, CD34." (PMID 32647229, 2020). "Consequently, CD34 expression was neither associated with primary tumor size and localization (pT stage, P = 0.368) nor with lymphonodal spread (pN stage, P = 0.679)." (PMID 31760702, 2020). "This larger study population with long-term follow-up emphasizes that the absence of CD34+ fibroblasts in the tumor stroma of a subset of ILC is associated with the presence of αSMA+ myofibroblasts and therefore indicates a phenotypic switch to cancer-associated fibroblasts (CAFs) for this subgroup." (PMID 32435886, 2020). "CD34 is a well-known marker of angiogenesis and endothelial progenitor cells, whilst VWF is a multimeric plasma glycoprotein that mediates platelet adhesion to both the subendothelial matrix and endothelial surfaces and is associated with tumor survival and angiogenesis." (PMID 31803626, 2019). "However, CD34+ losses in the current experimental setup are too high and acoustophoretic properties of CD34+ cells need to be investigated in more detail to improve recovery in the tumour cell depletion setting." (PMID 31217534, 2019). "Finally, the analysis of human tumor samples showed an association between Snail1 expression in the stromal compartment and the angiogenesis marker CD34, but not with CD31." (PMID 30250018, 2018). "Another commonly used approach is to produce DCs from CD34+ hematopoietic stem and progenitor cells (HSPCs), which have an extensive proliferation capacity to generate antigen presenting cells (APCs) with a primary DC phenotype and the capacity to induce robust anti-tumor T cell responses." (PMID 29867960, 2018). "As VE-cadherin is also expressed by endothelial cells, which are usually found in the tumours, we tested only samples with low expression of CD34, a marker of endothelial cells, to discard tumours with an excessive angiogenesis that might lead to confusing results." (PMID 27966446, 2017). "Weak to moderate PSMA immunoreactivity of PDAC tumor cells was detected in 5.3% of cases, while PSMA expression in tumor-associated neovasculature (cutoff PSMA+/CD34+ vessel ratio > 0.05) could be detected in 63.2% (weak/moderate in 33.4% and strong in 29.8% of cases, resp)." (PMID 29209626, 2017). "Interestingly, tumor cells with low CD34 expression displayed greater tumorigenicity than cells with high CD34 expression in the Tgfbr2 cKO + Hras backskin SCC, whereas we observed a dramatic enrichment for tumorigenicity in CD34+ SCC cells from transition zone tumors." (PMID 28219480, 2017). "Moreover, CD34 was concentrated at the tumour- adjacent mucosa sites." (PMID 29069745, 2017). "Importantly, we observed a pronounced decrease in tumor vasculogenic mimicry in the galunisertib-treated xenografts noted by the percentage of PAS-CD34+/PAS+CD34+ cells identified using immunohistochemistry (NTC group 0.43 ± 0.07, N = 5 vs. galunisertib-treated group 0.17 ± 0.03, N = 4, P = 0.0085)." (PMID 26976322, 2016). "Finally, angiogenesis in tumor tissues was evaluated by CD34 immunohistochemistry." (PMID 27825114, 2016).